UBALD2 (UBA like domain containing 2)
Synonyms: FAM100B; MGC29814
Tractability: No criterion of Open Targets' tractability assessment is met for any kind of drug.
Gene: Protein-coding gene on chromosome 17 (76,265,348 to 76,271,298, forward strand). Ensembl gene ENSG00000185262.
Genetic constraint (gnomAD): Loss-of-function variants: 8 observed, 6.73 expected, observed/expected ratio (o/e) 1.19, 90% interval 0.69 to 1.85. That is too few expected variants to judge how well the gene tolerates losing a copy. Missense variants: 137 observed, 144.6 expected, observed/expected ratio (o/e) 0.95, 90% interval 0.82 to 1.09. Synonymous variants: 88 observed, 63.29 expected, observed/expected ratio (o/e) 1.39, 90% interval 1.17 to 1.66.
Homologues: Orthologues: chimpanzee UBALD2 (100% identical), macaque UBALD2 (99% identical), dog UBALD2 (95% identical), guinea pig UBALD2 (93% identical), pig UBALD2 (93% identical), mouse Ubald2 (90% identical), tropical clawed frog ubald2 (76% identical), rat Ubald2 (73% identical), zebrafish ubald2 (70% identical). Paralogues in human: UBALD1 (66% identical).
Diseases named in the same sentence as UBALD2 in open-access papers:
UBALD2 is named in the same sentence as 2 diseases in open-access papers, as found by Europe PMC text mining. Sharing a sentence is not in itself a finding about the gene and the disease. The quoted sentences say what the papers report.
psoriasis (1 paper, 2021). An autoimmune condition characterized by red, well-delineated plaques with silvery scales that are usually on the extensor surfaces and scalp. "The biology of the other top DEGs according to their FDR value (ERV3-1, LSMEM1 and UBALD2) has not been extensively investigated and, to our knowledge, no specific relationships to CVD and psoriasis have been reported." (PMID 34639156, 2021).
inflammation (1 paper, 2021). Aberrant reaction of the microcirculation characterized by movement of fluid and leukocytes from the blood into extravascular tissues. "CEACAM1 correlated with vascular inflammation in the aorta, and CEACAM1, MMP9, MPO, ERV3-1, UBALD2 and LSMEM1 correlated with vascular inflammation in the carotid arteries." (PMID 34639156, 2021).